TLR4 (toll like receptor 4)
Diseases named in the same sentence as TLR4 in open-access papers (continued):
Sharing a sentence is not in itself a finding about the gene and the disease.
cryptococcal infection (5 papers, 2007 to 2023). "Taken together, TLR2 and TLR4 signals, independently of their limited role in host response against cryptococcosis, are useful in the modulation of innate immune response over time during Cryptococcus spp." (PMID 33304649, 2020). "However, to date, the precise role of individual TLRs, including TLR4, during cryptococcal infection is poorly understood." (PMID 37580395, 2023). "TLR2−/− and TLR-4−/− mice infected with C. neoformans show normal pro-inflammatory cytokine responses and similar survival rates to their wild type counterparts, and there are no reports of cryptococcal infections associated with their deficiencies." (PMID 37998856, 2023). "While TLR2 and TLR4 can be activated by cryptococcal components, these receptors do not play major roles in the defense against cryptococcal infections." (PMID 37998856, 2023). "More recently MyD88 and TLR2 but not TLR4 were shown to be required for host defense against Cryptococcus neoformans infection." (PMID 17982419, 2007).
cutaneous melanoma (5 papers, 2017 to 2023). A primary melanoma arising from atypical melanocytes in the skin. "It is reported that there are 6.1% of patients with cutaneous melanoma harboring TLR4 non-synonymous mutations." (PMID 32312954, 2020). "The aim of this study was to evaluate whether Saccharomyces cerevisiae-derived zymosan-modulated skin melanoma progression by regulation of TLR-2 and TLR-4 expression in peritoneal macrophages and serum TNF-α level." (PMID 29588627, 2018).
duodenal ulcer (5 papers, 2014 to 2025). An ulcer in the duodenal wall. "Electroacupuncture and omeprazole may prevent stress ulcers through a combination of antioxidant and anti-inflammatory actions, and by inhibition of the TLR4/MyD88/NF-κB signaling pathway." (PMID 33628315, 2021). "Expression of TLR4 and MyD88 was significantly reduced in the electroacupuncture group compared with the omeprazole group, indicating that the preventive effect of electroacupuncture on stress ulcers may be exerted specifically via suppression of the TLR4/NF-κB signaling pathway." (PMID 33628315, 2021). "The TLR4 +896 mutants were associated with duodenal ulcers in a study, which, however, had technical problems, as in over 40% of the duodenal ulcer patients the TLR4 +896 polymorphism could not be analyzed." (PMID 26161647, 2015).
encephalitis (5 papers, 2014 to 2022). An acute inflammatory process affecting the brain parenchyma. "Also, the ablation of both TLR3 and TLR4 molecules induced a highly increased susceptibility to encephalitis caused by JEV infection (p = 0.0122)." (PMID 25188232, 2014). "Taken together, these results demonstrate that TLR3-induced signal pathway is essential for the control of neuroinflammation caused by JEV infection, while TLR4 molecules may be dispensable to provide resistance to fatal encephalitis." (PMID 25188232, 2014). "In addition, we analyzed if the kind of lesion (i.e. encephalitis versus brain tumor) had an effect on protein expression levels (TLR4, HMGB1, HSP70 and NeuN) within the group of structural epilepsy." (PMID 31959173, 2020). "In relation to general encephalitis, omega-3 supplementation demonstrated neuroprotective effects against traumatic brain injury by reducing microglial activation and regulating the Toll-like receptor 4 (TLR4)/NF-kB signaling pathway." (PMID 31035457, 2019). "However, because induction of BBB is a relatively late and critical event in viral encephalitis, TLR4 may be a potential target for the development of therapeutics for encephalitic alphaviruses." (PMID 33487119, 2021).
endometrial cancer (5 papers, 2008 to 2025). Primary or metastatic malignant neoplasm involving the endometrium (mucous membrane that lines the endometrial cavity). "Finally, to mimic the chronic inflammatory signals predisposing to endometrial cancer, we simultaneously treated benign organoids, which express LPS receptor, TLR-4 (Toll-like receptor 4), with E. coli- derived LPS (O111:B4) and increasing LCC media concentrations for 24 h." (PMID 38951935, 2024). "Ten polymorphisms were genotyped in 191 endometrial cancer cases and 291 controls using real-time PCR: NOD1 (rs2075822, rs2907749, rs2907748), NOD2 (rs5743260, rs2066844, rs2066845), TLR2 (rs5743708), TLR4 (rs4986790) and TLR9 (rs5743836, rs187084)." (PMID 20646321, 2010). "Kaplan-Meier survival analysis and T-tests were used to evaluate the influence of the NOD1, NOD2, TLR2, TLR4 and TLR9 polymorphisms on the age of diagnosis of endometrial cancer." (PMID 20646321, 2010). "For these reasons, we sought to determine if genetic variation in a number of TLRs and NOD genes (TLR2, TLR4, TLR9, NOD1 and NOD2) were associated with risk of developing endometrial cancer." (PMID 20646321, 2010). "TLR3 and TLR4 proteins in hyperplasia and endometrial carcinoma were mostly localized to the luminal and glandular epithelium." (PMID 18775079, 2008). "With respect to the TLRs, TLR2, TLR4 and TLR9 are highly polymorphic and represent interesting targets to elucidate their role in endometrial cancer development." (PMID 20646321, 2010).
Giardia infection (5 papers, 2021 to 2025). "Collectively, TLR4-mediated ROS production seems to regulate A20 expression and control pyroptotic outcomes in response to Giardia infection." (PMID 34943932, 2021). "Importantly, studies have revealed the functions and mechanisms associated with the innate immune responses mediated by TLR2 and TLR4 during Giardia infection." (PMID 34336841, 2021). "In addition, like HSP70, TLR4 could also mediate inhibition of CASP-9 and CASP-8 activation, expanding the HSP70-mediated anti-apoptotic signaling network during Giardia infections." (PMID 36937289, 2023). "Yet, unlike TLR4, TLR2 served as an apoptosis promoter during Giardia infections." (PMID 36937289, 2023).
Gliosis (5 papers, 2014 to 2025). Gliosis is the focal proliferation of glial cells in the central nervous system. "Similar to the results for mRNA levels of inflammatory markers, the peak in levels of mRNA associated with gliosis in Ins2Akita/+ mice appeared at 12 weeks of age, with increases in Tlr4 (encoding TLR4), Pcan and Mmp14 (encoding matrix metalloproteinase 14)." (PMID 37670018, 2023). "Additionally, it was of interest to reaffirm whether TLR4 is the target for how ultra-low dose (+)naloxone attenuates opioid-induced gliosis and morphine-induced hyperalgesia." (PMID 24824631, 2014).
glomerulosclerosis (5 papers, 2015 to 2025). A hardening of the kidney glomerulus caused by scarring of the blood vessels. "Downregulation of TLR4 and its downstream signaling shifts macrophage polarization from an M1 towards an M2 phenotype and ameliorates renal interstitial fibrosis, glomerulosclerosis, and renal functional loss in the early stages of UUO and adriamycin nephropathy in rats." (PMID 32660446, 2020). "In addition to increased albuminuria and loss of kidney function, TLR4 WT mice also developed significant kidney histological damage at 4 weeks after 5/6Nx+AngII, as assessed by increased glomerulosclerosis and interstitial fibrosis scores." (PMID 26416975, 2015). "Additionally, the downregulation of TLR4 and its signaling pathway promotes a shift in macrophage polarization from the proinflammatory M1 phenotype to the anti-inflammatory M2 phenotype, which helps reduce renal interstitial fibrosis, glomerulosclerosis, and loss of kidney function." (PMID 40362229, 2025). "We recently reported that the glomerular endothelium of diabetic mice expresses TLR2 and TLR4, and that the TLR2/4-ligand P. gingivalis LPS causes glomerulosclerosis in diabetic mice with the accumulation of type 1 collagen and inflammatory cytokines in glomeruli." (PMID 33407253, 2021). "Although significant glomerulosclerosis was not yet present, DM rats already exhibited augmented renal content of TLR4, higher nuclear translocation of the p65 subunit, while p65 was detected in the glomerular area." (PMID 32116790, 2020).
Granuloma (5 papers, 2017 to 2025). A compact, organized collection of mature mononuclear phagocytes, which may be but is not necessarily accompanied by accessory features such as necrosis. "However, the levels of CXCL10 and CCL5, readout cytokines of the MyD88-independent TLR4 pathway increased at week 5 when Sj eggs induce granuloma and then at week 6 when Sj eggs induce acute liver damage." (PMID 29321784, 2017). "IL-17A was the highest positively correlated gene to periapical granuloma, while TLR2, TLR4, VEGF, and MMP-9 were negatively correlated with the enriched pathways of granuloma." (PMID 34539639, 2021).
hearing loss (5 papers, 2009 to 2026). "In a multigene analysis, combined carriership of the TLR2+2477 wild type (WT) with TLR4+896 mutant alleles increases the risk of hearing loss (p<0.0001, OR 5.7 in BM and p = 0.0001, OR 7.6 in MM)." (PMID 22662111, 2012). "TLR4+896 AG or GG alleles were associated with a significantly increased risk of hearing loss (p = 0.001, OR 4.0, 95% CI 1.7–9.4) especially in MM patients (p = 0.0004, OR 6.2 95% CI 2.0–19.5), but was not significant for PM patients." (PMID 22662111, 2012). "As anticipated, LPS induced Toll Like Receptor 4 (TLR4) signaling and augmented IL-1β expression and was associated with hearing loss." (PMID 19401759, 2009). "In vivo, CS-PB pretreatment (2 mg/mL, 2 μL) was administered by carefully applying the solution to the round window membrane (RWM) using a microsyringe in a noise-induced hearing loss rat model, which significantly curtailed the noise-induced activation of the TLR4/NF-κB pathway in the cochlea." (PMID 42093999, 2026). "TLR4 represents a potential therapeutic target for sensorineural hearing loss." (PMID 40325385, 2025). "Combined carriership of TLR2+2477 GG WT and TLR4+896 AG mutant alleles significantly increases the risk to develop hearing loss in BM (p<0.0001, OR 5.7, 95% CI 2.3–14.4, in MM patients: p = 0.0001, OR 7.6, 95% CI 2.3–24, in PM patients: p = 0.03, OR 13.9, 95% CI 1.3–147)." (PMID 22662111, 2012). "Carriage of one or both mutant alleles in TLR4+896 and TLR9 -1237 increases the risk for hearing loss (p = 0.0006, OR 4.1 in BM)." (PMID 22662111, 2012). "S100A8 is the endogenous ligand for Toll like receptor 4 (TLR4) which activates NF-ĸB, whereas LCN2 is an NF-ĸB target gene and pro-inflammatory cytokine, that can itself activate the NF-ĸB pathway and is implicated in inflammation, neurodegeneration and noise-induced hearing loss." (PMID 30106954, 2018).
herpes zoster (5 papers, 2020 to 2025). A common dermal and neurologic disorder caused by reactivation of the varicella-zoster virus that has remained dormant within dorsal root ganglia, often for decades, after the patient's initial exposure to the virus in the form of varicella (chickenpox). "In recent years, the U.S. FDA has approved several TLR adjuvanted vaccines, including TLR4 based HPV vaccine (Cerarix) and zoster vaccine (Shingrix), and TLR9 based HBV vaccine (Heplisav)." (PMID 34766005, 2021). "The adjuvant recombinant zoster vaccine (Shingrix, GSK plc, London, UK) contains a recombinant glycoprotein E (gE) and AS01B Adjuvant System, consisting of a liposomal formulation of monophosphoryl lipid A (MPL), a toll-like receptor 4 (TLR4) agonist, and QS-21, a purified plant extract." (PMID 40308434, 2025).
hypertriglyceridemia (5 papers, 2024 to 2025). A laboratory test result indicating elevated triglyceride concentration in the blood. "By affecting different immune niches in the liver and SkM, S100A9 rescues hypertriglyceridemia and hyperketonemia and stimulates SkM glucose uptake via Toll-like-receptor 4 (TLR4)-dependent mechanism." (PMID 40874857, 2025). "Treating ID mice with the protein S100A9 rescues the polarization and lipid-related changes caused by ID in the Kupffer cells, and, through them, rescues hypertriglyceridemia and hyperketonemia in a TLR4-dependent manner." (PMID 40874857, 2025). "In conclusion, S100A9's ability to normalize hyperketonemia and hypertriglyceridemia in ID is primarily driven by TLR4 signaling in KCs, uncovering a novel mechanism for regulating metabolic dysfunction." (PMID 40874857, 2025). "The conclusion that TLR4 in the KCs mediates the ketone/lipid improving action of S100A9 is strongly supported by the fact that re-expression of TLR4 in KCs of ID mice is sufficient for virtually all of the hyperketonemia- and hypertriglyceridemia-lowering effect of S100A9." (PMID 40874857, 2025). "For example, in the gut microbiota regulated by hypertriglyceridemia (HTG), glycerophospholipid metabolism is upregulated, which may affect the body’s metabolic status in a TLR4-dependent manner." (PMID 41277976, 2025).
insulinoma (5 papers, 2011 to 2021). "Asprosin incubation promotes inflammation reaction via the TLR4/JNK-mediated signal pathway in insulinoma cells and human islets." (PMID 33933135, 2021). "In order to confirm the effects of TLR4 activation in β-cells, we assessed LPS-induced stimulation of TLR4 expression in MIN-6 mouse insulinoma cells." (PMID 21356084, 2011). "We investigated whether TLR4 is present in β-cells purified from freshly isolated human islets and confirmed the results using MIN6 mouse insulinoma cells, by analyzing the effects of TLR4 expression on cell viability and insulin homeostasis." (PMID 21356084, 2011).
Intraventricular hemorrhage (5 papers, 2020 to 2022). Bleeding into the ventricles of the brain. "Nonetheless, in a rat model of hemorrhagic hydrocephalus, intraventricular hemorrhage causes a Toll-like receptor 4 (TLR4)- and NF-κB-dependent inflammatory response in CPe associated with ~3-fold increase in bumetanide-sensitive CSF secretion." (PMID 31911626, 2020). "Previous research has discovered that intraventricular hemorrhage can cause a Toll-like receptor 4 (TLR4)- and NF-κB-dependent inflammatory response." (PMID 32714131, 2020). "In a rat model established with PHH, the investigators demonstrated that intraventricular hemorrhage (IVH) leads to toll-like receptor 4 (TLR4) and nf-kb-dependent inflammatory responses in the CPE." (PMID 36340696, 2022). "We speculate that the TLR4/NF-κB signaling pathway may be involved in the pathogenesis of GBS following intraventricular hemorrhage." (PMID 32714131, 2020). "Thus, the TLR4 and NF-κB signaling pathway may be involved in the pathogenesis of GBS after intraventricular hemorrhage." (PMID 32714131, 2020). "The TLR4 and NF-κB signaling pathway may be involved in the pathogenesis of GBS after intraventricular hemorrhage, but additional research and information is required to prove this pathway’s involvement in the development of GBS after intraventricular hemorrhage." (PMID 32714131, 2020).
iron deficiency (5 papers, 2018 to 2025). "F. nucleatum induced chemokine production via TLR4/NF-κB signaling, which was inhibited by iron deficiency." (PMID 36136589, 2022). "Iron deficiency can alter signalling via the toll-like receptor 4 (TLR4) pathway and affect the activity of iron-dependent ubiquitin ligase and regulation of SHP1 (Src homology region 2 domain-containing tyrosine phosphatase)." (PMID 36364955, 2022). "Conversely, iron deficiency promoted type 1 pro-inflammatory cytokine expression in response to TLR4 stimulation." (PMID 29771935, 2018). "In addition, F. nucleatum induced CCL8 expression in macrophages via the TLR4/NF-κB signaling pathway, which was inhibited by iron deficiency." (PMID 36136589, 2022). "Given that DFO treatment is suitable for effectively evaluating the roles of intracellular iron in THP-1 cells under cell culture conditions, we examined the effects of iron deficiency to explore the link between iron and TLR4/NF-κB signaling in the following experiments." (PMID 36136589, 2022). "LPS increased CYBRD1 (p < 0.001) and IL8 (p = 0.004) and tended to elevate TLR4 and TNF expression (p ≤ 0.07), while iron deficiency upregulated IL8 expression (p < 0.001)." (PMID 41295277, 2025). "In addition, possible correlation between the monomeric Toll-like Receptor 4 (TRL4) and the antagonistic penta-acylated lipid A of LPS could contribute to novel strategies to tackle this nutrition disorder." (PMID 33467503, 2021).
itch (5 papers, 2014 to 2025). "Our data demonstrated that i.t. administration of TLR4 antagonist was highly effective in reducing pruritus in both early and late phases, whereas intratumoral injection of the same antagonist was not effective." (PMID 36520531, 2023). "We examined the involvement of TLR4 in CTCL-induced itch by testing the effects of 20 μg of the TLR4 antagonist LPS Rhodobacter sphaeroides (LPS-RS) in both sexes." (PMID 36520531, 2023). "In this study, we have investigated the roles of TLR4 in sensory transmission and found that TLR4 is required for optimal histamine-induced itch signal transduction through regulating TRPV1 activity." (PMID 25139109, 2014). "Consequently, this process significantly activates peripheral TLR4 signaling and exacerbates skin itchiness." (PMID 38491103, 2024). "In our study, TLR4 regulates histamine-induced and chloroquine-induced itch by distinct mechanisms." (PMID 25139109, 2014). "IMO stress-induced itch aggravation in TMA-treated AD mice might be attributed to the translocation of gut-derived bacterial cells and LPS, which activates peripheral TLR4 signaling." (PMID 38491103, 2024).
Listeria infection (5 papers, 2009 to 2022). "It was observed that inhibition of TLR4 (as opposed to TLR2) in Nr1i2-/- mice could decrease TNF-α and IL-6 levels, which is consistent with the result that Pxr-/-Tlr4-/- mice (compared with Pxr-/-Tlr2-/- mice) could effectively protect against Listeria monocytogenes infection." (PMID 36119030, 2022). "E. coli has been shown to activate TLR4 and NOD1, whereas resistance to Listeria infection was related to the presence of functional NOD2, indicating that this receptor is engaged by HKLM." (PMID 19193240, 2009). "Thus, IFN-β induction in response to Listeria infection relies in part on TLR3 and does not require TLR4." (PMID 22432012, 2012).
lung squamous cell carcinoma (5 papers, 2017 to 2025). "The stromal tissue of squamous cell lung cancer is enriched for fibronectin, myofibroblasts, and IL8, supporting a model of myofibroblast generated contractile force placing fibronectin under sufficient strain to trigger the activation of TLR4 signaling." (PMID 31952223, 2020).
malnutrition (5 papers, 2011 to 2023). Inadequate nutrition resulting from poor diet, malabsorption, or abnormal nutrient distribution. "However, lymphoid involution out of proportion with weight loss is a consistent feature of acute pre-pubescent malnutrition, and this phenomenon extends to the compartment of cells known to both express TLR-4 and produce IL-10." (PMID 21318019, 2011). "As a gram-negative bacteria sensor, downregulation of TLR4 during malnutrition suggests decreased ability to recognize and respond to infections, including those caused by Escherichia coli." (PMID 32525953, 2020). "The current study showed that MR prevents LPS-induced ALI, including the inflammatory response, inflammatory cell infiltration, and alveolar epithelial cell injuries without malnutrition via upregulating the CSE/H2S pathway, which is likely associated with inhibition of the TLR4/NF-κB/NLRP3 pathway." (PMID 35057502, 2022).